HSF1 (heat shock transcription factor 1)
Diseases named in the same sentence as HSF1 in open-access papers (continued):
Sharing a sentence is not in itself a finding about the gene and the disease.
influenza (2 papers, 2017 to 2018). An acute viral infection of the respiratory tract, occurring in isolated cases, in epidemics, or in pandemics; it is caused by serologically different strains of viruses (influenzaviruses) designated A, B, and C, has a 3-day incubation period, and usually lasts for 3 to 10 days. "Altogether, these data reveal that HSF1-regulated chaperones can define the fitness of biophysically destabilized immune escape variants in influenza." (PMID 30222731, 2018). "Here, we not only define a new role for host proteostasis in influenza evolution, but we also show that two unique proteostasis perturbations, HSF1 activation and Hsp90 inhibition, have distinctive consequences for client protein evolution." (PMID 28949290, 2017). "At both permissive (37°C) and biophysically restrictive, fever-like (39°C) temperatures, chemical induction of the HSF1 inhibitor reduces cytosolic chaperone transcript and protein levels in both the absence and presence of influenza." (PMID 30222731, 2018). "Indeed, by passage 11, the first passage at which we observe fixed mutations in any environment, the shape of the non-synonymous SFS for influenza evolved in the Hsp90-inhibited environment is significantly different from that of influenza evolved in the basal and HSF1-activated environments." (PMID 28949290, 2017). "Notably, the condition in which HSF1 was inhibited (HSF1i) did not significantly alter the replication of wild-type influenza or host cell metabolic fitness over the course of our experiment." (PMID 30222731, 2018). "Importantly, monitoring chaperone levels in the context of influenza A/Wuhan/1995 (H3N2) infection shows that, under our infection conditions, influenza itself neither induces heat shock protein transcripts nor interferes with our method to activate HSF1." (PMID 28949290, 2017).
injury (2 papers, 2020 to 2021). Damage inflicted on the body as the direct or indirect result of an external force, with or without disruption of structural continuity. "We have unveiled here an important role of HSF1 in acute lung injury (ALI)." (PMID 33381262, 2020). "A recent study demonstrated that Notch1 signaling promoted HSF1 activation, which in turn inhibited NLRP3 function and hepatocellular apoptosis, leading to the alleviation of I/R-induced liver injury." (PMID 34504645, 2021).
kidney damage (2 papers, 2023). "Further, the present data revealed two alternatively spliced genes, namely Sirtuin 2 (SIRT2) and Heat Shock Transcription Factor 1 (HSF1) entangled in response to oxidative stress, encoding factors that are activated for instance in kidney damage." (PMID 38074096, 2023).
lentivirus infection (2 papers, 2015 to 2024). Virus diseases caused by the Lentivirus genus. "MYCN mRNA and protein levels were decreased after knockdown of HSF1 and recovered after lentivirus infection." (PMID 39248163, 2024). "After knockdown of HSF1 with siRNAs, MYCN expression was restored by lentivirus infection." (PMID 39248163, 2024).
liver inflammation (2 papers, 2020 to 2021). "The disruption of HSF1 reduced Snail activation and enhanced NLRP3 activation, while the adoptive transfer of HSF1-expressing macrophages to Notch1M-KO mice augmented Snail activation and mitigated IR-triggered liver inflammation." (PMID 31673056, 2020). "In contrast, the adoptive transfer of HSF1-expressing macrophages to myeloid-specific Notch1 knockout mice promoted Snail activation and alleviated IR-triggered liver inflammation, which suggests that the Notch1/HSF1/Snail axis is a therapeutic target for liver inflammatory injury." (PMID 34239690, 2021). "Our results highlight the importance of JAG1-mediated myeloid Notch1/HSF1/Snail signaling as a key regulator of NLRP3 activation and cell apoptosis during IR stress-mediated liver inflammation." (PMID 31673056, 2020). "We demonstrate that myeloid Notch1 signaling promotes heat shock transcription factor 1 (HSF1) and Snail activation, which in turn controls NLRP3-mediated innate immunity during IR-triggered liver inflammation." (PMID 31673056, 2020).
lung adenocarcinoma (2 papers, 2017 to 2024). A carcinoma that arises from the lung and is characterized by the presence of malignant glandular epithelial cells. "For this purpose, we utilized the human lung adenocarcinoma A549 cell line and genetically modified it by knockdown of Hsp70 or HSF1, and the H1299 cell line with knockdown or overexpression of Hsp70." (PMID 39201776, 2024).
lymph node metastasis (2 papers, 2018 to 2024). "Patients with high HSF1 expression had larger tumour size (P = 0.001), advanced Bornmann classification (P = 0.002), advanced depth of invasion (P = 0.015), lymph node metastasis (P<0.001), distant metastasis (P = 0.011) and tumour-node-metastasis (P<0.001)." (PMID 30326922, 2018). "In addition, the univariate analysis revealed a significant difference in survival for lymph node metastasis, lung metastasis, tumor number, and HSF1 levels." (PMID 39243039, 2024). "Furthermore, multivariate analysis showed a significant difference in HSF1 levels occurring only for survival, lymph node metastasis, and lung metastasis." (PMID 39243039, 2024).
male infertility (2 papers, 2021 to 2024). The inability of the male to effect fertilization of an ovum after a specified period of unprotected intercourse. "A single study on HSF2 gene in this context is known.Therefore, it is of interest to document data on the link between male infertility and HSF1, HSF2 and UBE2I gene polymorphisms." (PMID 35540693, 2021). "Thus, a representative analysis of variants/mutations of HSF1, HSF2 andUBE2I genes in multiple cohorts along with their functional assay will provide insights into the cause of male infertility." (PMID 35540693, 2021). "Thus, although previous studies have demonstrated that the HSF1 and HSF2 genes are indispensable for spermatogenesis, their functional insights into genotype sequencing and male infertility are still inconsistent." (PMID 38791628, 2024). "On the basis of the genotypic analysis of our findings, we could not find any relationship between rs78202224 (C>A),rs139496713 (C>T) and rs45504694 (C>A) SNPs in HSF1 and HSF2 genes and male infertility." (PMID 35540693, 2021).
malignant peripheral nerve sheath tumor (2 papers, 2025 to 2026). Malignant peripheral nerve sheath tumor (MPNST) is a rare and often aggressive soft tissue sarcoma occurring in a wide range of anatomical sites. "In Neurofibromatosis type I (NF1)-deficient malignant peripheral nerve sheath tumor (MPNST) cells, HSF1 loss induces widespread protein polyubiquitination, aggregation, and tumor-suppressive amyloidogenesis, yet is dispensable in non-transformed Schwann cells." (PMID 41835397, 2026).
malnutrition (2 papers, 2021 to 2022). Inadequate nutrition resulting from poor diet, malabsorption, or abnormal nutrient distribution. "Our study suggested that LBE may be a potential antiaging natural dietary supplement especially to individuals with malnutrition or chronic diseases and a potential therapeutic agent for neurodegenerative diseases characterized by hsf-1 deficiency." (PMID 35096951, 2021).
neurofibroma (2 papers, 2013 to 2023). An intraneural or extraneural neoplasm arising from nerve tissues and neural sheaths. "Given that the loss of neurofibromin activates HSF1 to promote carcinogenesis, a finding that plexiform neurofibroma cell lines are sensitive to HSP90AB1 inhibitors is not entirely unexpected, and the potential for heat shock protein inhibitors as NF1 treatments has been suggested." (PMID 38136356, 2023).
osteoporosis (2 papers, 2022 to 2023). A condition of reduced bone mass, with decreased cortical thickness and a decrease in the number and size of the trabeculae of cancellous bone (but normal chemical composition), resulting in increased fracture incidence. "Compared with the control group, the expression of HSF1 in MSCs of osteoporosis mice was higher, and the expression of SLC40A1 was lower." (PMID 37770229, 2023).
ovarian epithelial tumor (2 papers, 2021 to 2023). A benign, borderline, or malignant tumor that originates from the surface epithelium of the ovary. "The results demonstrated that the highest alteration frequency of HSF1 was approximately 27% in patients with ovarian epithelial tumors." (PMID 34239690, 2021).
pancreatitis (2 papers, 2021 to 2022). Inflammation of the pancreas. "In the same direction, heat shock factor protein 1 (HSF-1) knockout mice with defects in HSPs synthesis were reported to be more severely affected by cerulein-induced pancreatitis." (PMID 36034701, 2022). "We mainly used pancreatic acinar cell 3-dimensional (3D) culture and a spontaneous pancreatic precancerous lesion mouse model called LSL-KrasG12D/+; Pdx1-Cre (KC) (and pancreatitis models derived from KC mice) to explore the pro-tumorigenesis mechanisms of the HSF1 in vitro and in vivo." (PMID 33422093, 2021). "Mentionable, HSF1/HSPs are important for the maintenance of the proteostasis of cells (including normal pancreatic acinar cells) in various stress condition and protect them against the damage of PTSs such as pancreatitis." (PMID 33422093, 2021). "Interestingly, after we treated mice with KRIBB11 to inhibit the activation of HSF1, the formation of pancreatitis-induced ADM, PanINs and PDAC was partly blocked in vivo, like the in vitro experiments with pancreatic acinar cell 3D culture." (PMID 33422093, 2021).
primary effusion lymphoma (2 papers, 2018). A large B-cell lymphoma located in the body cavities, characterized by pleural, peritoneal, and pericardial fluid lymphomatous effusions and that is always associated with human herpes virus-8 (HHV-8). "Indeed, down-regulation of the expression of HSF1/Hsp70 by STAT3 inhibitor AG490 suppressed Mcl-1 and led to the induction of apoptosis and autophagy in primary effusion lymphoma cells." (PMID 29541415, 2018).
prostate adenocarcinoma (2 papers, 2023 to 2024). "HSP90AA1 gene expression was not significantly correlated with the gene expression of HSF1, HSF2, and HSF5 in prostate adenocarcinoma specimens." (PMID 36982267, 2023).
schizophrenia (2 papers, 2015 to 2021). A major psychotic disorder characterized by abnormalities in the perception or expression of reality. "Single cell RNA detection revealed augmented cell-to-cell variable activation of HSF1-HSP signaling in the schizophrenia patients' neural progenitor cells, individual cell lines of which carry different genetic risks for schizophrenia." (PMID 26074774, 2015).
varicocele (2 papers, 2019 to 2025). A condition characterized by the dilated tortuous veins of the spermatic cord with a marked left-sided predominance. "Previous studies showed increased levels of HSF1 mRNA in the sperm of men with varicocele and with oligozoospermia and that its protein levels significantly increased after oxidative stress induction." (PMID 40497989, 2025). "Despite the increased levels of HSF1 mRNA that were observed in the sperm of men with varicocele and with oligozoospermia, the presence of this protein in human ejaculated spermatozoa was never reported." (PMID 31694346, 2019).
-dependent (1 paper, 2021). "Furthermore, genes activated by ERα and HSF1 play an important role in regulating the growth and spread of estrogen-dependent tumors." (PMID 34783649, 2021).
adenovirus infection (1 paper, 2018). "HSF1 and HSF1-AB, a deletion mutant of HSF1 lacking the entire trimerization domain (156–226 aa), were overexpressed in CGNs for 40 hours via adenovirus infection followed by HK (high potassium) or LK (low potassium) treatment for 8 hours." (PMID 30467350, 2018).
adrenal carcinoma (1 paper, 2015). A carcinoma involving a adrenal gland. "Instead, we used human adrenal carcinoma H295R cells that express high levels of endogenous hSF-1 and found that similar to exogenously expressed hLRH-1, TA decreases levels of sumoylated hSF-1 in H295S cells." (PMID 26653140, 2015).
age (1 paper, 2018). A temporal measurement of the time period elapsed since an identifiable point in the life cycle of an organism. "Impairment of HSF1 activity and loss of protein chaperone function have been reported to occur with ageing and in the setting of age-related neurodegeneration." (PMID 29973287, 2018).
age-related hearing loss (1 paper, 2021). "Heat shock factor 1 (HSF1) plays a critical role in ER stress; however, its exact function in age-related hearing loss (ARHL) has not been fully elucidated." (PMID 34572102, 2021).
Anxiety (1 paper, 2021). Intense feelings of nervousness, tension, or panic often arise in response to interpersonal stresses. "Previous work showed working memory deficits in Hsf1(−/−) mice and a resemblance in several other behavioral abnormalities between Hsf1(+/−) and Hsf1(−/−) mice, including enhanced vulnerability to repeated stress exposure, reduced anxiety-like behavior, and altered locomotion activity." (PMID 34884918, 2021). "Previous studies in Hsf1(−/−) mice showed reduced PSD-95, aberrant synapse formation, impaired spinogenesis in the hippocampus, and several behavioral alterations including reduced anxiety and working memory deficits." (PMID 34884918, 2021).
arteriosclerosis (1 paper, 2020). A vascular disorder characterized by thickening and hardening of the walls of the arteries. "Presence of arteriosclerosis associated significantly with expression of SQLE, FDPS, MVD, HMGCS1, HSD17B7 and HSF1 (all p≤0.05)." (PMID 32353828, 2020).
astrocytoma (1 paper, 2023). "Clustered cell populations in astrocytoma also exhibited a modest overlap of DYRK2 and HSF1." (PMID 36622366, 2023).
benign ovarian tumors (1 paper, 2016). "A previous study of 37 malignant vs. benign ovarian tumors has shown that HSF1 expression is higher in the malignant tumors." (PMID 27997575, 2016).
breast ductal carcinoma (1 paper, 2021). "To confirm these observations, we overexpressed HSF1 in T47D cells, a model of breast ductal carcinoma." (PMID 33593922, 2021).
Cerebral ischemia (1 paper, 2020). Restriction of arterial blood supply to the brain associated with insufficient oxygenation to support the metabolic requirements of the tissue. "A neuroprotective role of TTR has also been described under conditions of cerebral ischemia in mice deficient for heat shock transcription factor 1 (HSF1), an activator of heat-shock proteins." (PMID 33362465, 2020).
channelopathy (1 paper, 2025). Channelopathies are a group of diseases caused by the dysfunction of ion channel subunits or their interacting proteins. "Moreover, Piezo2 channelopathy likely promotes diminishing HSF1 function in the hippocampus in the presence of the identified HSF1 variant." (PMID 41155507, 2025). "Since Piezo2 channelopathy is suggested to be a principal transcription activator, it may not only impact adult hippocampal neurogenesis, but might activate non-coding heat shock RNA-1 (HSR1) in order to activate HSF1." (PMID 41155507, 2025).
chronic myelomonocytic leukemia (1 paper, 2023). A myelodysplastic/myeloproliferative neoplasm which is characterized by persistent monocytosis, absence of a Philadelphia chromosome and BCR/ABL fusion gene, fewer than 20 percent blasts in the bone marrow and blood, myelodysplasia, and absence of PDGFRA or PDGFRB rearrangement. "Of note, chronic myelomonocytic leukemia cells that are frequently associated with defective monocyte differentiation were lacking both HSF1 and PU1 expression." (PMID 36765939, 2023).
cognitive defects (1 paper, 2024). "HSF1 expression is decreased in AD patients, and overexpression of the active form of HSF1 in AD animal models reverses cognitive defects." (PMID 39519208, 2024).
COVID-19 (1 paper, 2024). A disease caused by infection with severe acute respiratory syndrome coronavirus 2. "Human coronaviruses activate and hijack the proteostasis guardian HSF1 to enhance viral replication, and FILIP1L is downregulated in COVID-19." (PMID 38674024, 2024).
cryptorchidism (1 paper, 2024). The failure of one or both testes of a male fetus to descend from the abdomen into the scrotum during the late part of pregnancy. "This suggests that, in most mammals, the inhibition of spermatogenesis during cryptorchidism is partly attributable to the activation of an HSF1/TDAG51-dependent mechanism." (PMID 39123737, 2024).
cutaneous squamous cell carcinoma (1 paper, 2017). "We found that the Michael acceptor bis(2-hydoxybenzylidene)acetone (HBB2), a dual activator of NRF2 and HSF1, protects against the development of UV irradiation-mediated cutaneous squamous cell carcinoma in mice." (PMID 28887499, 2017).
cyst (1 paper, 2018). A sac-like closed membranous structure that may be empty or contain fluid or amorphous material. "A second A. franciscana hsf1 cDNA with an identical ORF was cloned from a preparation of cyst RNA, thereby verifying the absence of PCR and sequencing artifacts (not shown)." (PMID 29979776, 2018).
depression (1 paper, 2016). "HSF-1 knockouts in mice show abnormal affective behavior, including increased susceptibility to depression-like behavior and aggression, and molecular chaperones are associated with a number of human diseases, including neurodegenerative disorders." (PMID 26773049, 2016).
diabetic retinopathy (1 paper, 2019). "The pleiotropic role of HSF1 warrants further investigation of whether it exhibits similar neuroprotective functions in other models of retinal diseases such as diabetic retinopathy, glaucoma, retinopathy of prematurity, and retinitis pigmentosa." (PMID 30884523, 2019).
diffuse large B-cell lymphoma (1 paper, 2023). "In diffuse large B-cell lymphomas (DLBCL), HSF1 mRNA is upregulated compared with regular B-cells, which can be one of the reasons for the strong expression of a wide variety of HSPs in this type of cancer." (PMID 36765939, 2023).
dilated cardiomyopathy (1 paper, 2017). Cardiomyopathy which is characterized by dilation and contractile dysfunction of the left and right ventricles. "To explore the potential role of HSF1 in the human cardiac fibrosis, we analyzed the activation and expression of HSF1 in the fibrotic hearts from dilated cardiomyopathy (DCM) patients." (PMID 28091697, 2017).
Down syndrome (1 paper, 2024). "Moreover, extensive clinical analysis could determine whether the misregulation of HSF1 is a hallmark of Down syndrome." (PMID 39116081, 2024).
endothelial dysfunction (1 paper, 2022). In vascular diseases, endothelial dysfunction is a systemic pathological state of the endothelium (the inner lining of blood vessels) and can be broadly defined as an imbalance between vasodilating and vasoconstricting substances produced by (or acting on) the endothelium. "Given that phosphorylated HSF1 is responsible for the activation of Hspa1a transcription, our findings suggested that Nar promoted iHSP70 expression via a HSF1-dependent mechanism, by which Nar protected HUVECs against HG-induced endothelial dysfunction." (PMID 35958293, 2022).
estrogen-receptor positive breast cancer (1 paper, 2022). "Analyses of The Cancer Genome Atlas data indicated that higher ATF3, FOS, and FOSB expression levels correlated with low HSF1 levels in estrogen receptor-positive breast cancer, reflecting higher heat shock-induced expression of these genes in HSF1-deficient MCF7 cells observed in vitro." (PMID 36010586, 2022).